TNF (tumor necrosis factor)
Diseases named in the same sentence as TNF in open-access papers (continued):
Sharing a sentence is not in itself a finding about the gene and the disease.
Obesity (continued). "In contrast to leptin, adiponectin is recognized as an anti-inflammatory factor, strongly inhibiting lipopolysaccharide-induced production of TNF-α in macrophages, and its expression is inversely correlated with obesity." (PMID 33557311, 2021). "During obesity, macrophages accumulate in the adipose tissue and shift to a pro-inflammatory state, exemplified by increased expression of IL-1β, TNF and IL-6." (PMID 34201844, 2021). "In obesity, the adipose tissue becomes hypertrophic and hyperplastic, triggering increased production of pro-inflammatory adipokines, such as tumor necrosis factor α, interleukin 6, interleukin 1, and leptin." (PMID 34283044, 2021). "Plasma levels of adiponectin can be reduced with the increase in pro-inflammatory cytokines such as TNF-α and IL-6, present in obesity, in addition to the levels of myostatin, a myokine that can elevate the adipose tissue mass." (PMID 33807959, 2021). "TNF-α, produced by macrophages, has also been targeted as a link between obesity and insulin resistance, as a TNF-α antagonist Etanercept causes improvements in fasting blood glucose levels in obese individuals with metabolic syndrome." (PMID 33670215, 2021). "The study in patients with modest obesity and early metabolic dysfunction reported that TNF-alpha in visceral adipose tissue was higher in the obese (BMI > 25 kg/m2)." (PMID 33946540, 2021). "A negative correlation was also observed between the total protein intake in PCOS patients and between overweight and obesity and the concentration of IL-6, TNF-α." (PMID 34441766, 2021). "During obesity, adipocytes increase pro-inflammatory cytokine and chemokine secretion of IL-6 and TNF-alpha, where TNF-alpha has been shown to increase insulin resistance in diet-induced obese mice." (PMID 34863096, 2021). "TNF-α is a proinflammatory cytokine that increases in aging and obesity, promotes protein degradation, decreases protein synthesis, and inhibits myogenic differentiation." (PMID 34676021, 2021). "As an example, placental inflammation and TNF levels were reported to be elevated in female placentas only, suggesting different placental inflammatory responses to obesity according to fetal sex." (PMID 33572203, 2021). "Children with obesity had a large scale of adipocytes, which promoted macrophage to accumulate and release of the proinflammatory cytokines, including IL-6, IL-1β, and TNF-α, which showed some degree of chronic inflammation." (PMID 34258058, 2021). "There is a well-recognised link between TNF-α and obesity, inflammation and diabetes and an increased expression of TNF-α is found in the adipose tissue of obese and insulin-resistant animal and human models." (PMID 33904577, 2021). "In this study, berberine treatment not only reduced obesity but also considerably decreased the concentration of TNF-α, iNOS, Cox-2, and Reg3γ." (PMID 35095784, 2021). "IL-6 and TNF-α are cytokines that links the obesity and liver cancer through chronic inflammation and contribute for development of chronic low-grade systemic inflammation." (PMID 34535145, 2021). "Obesity is characterized by an increased production of pro-inflammatory cytokines, such as interleukin-6 (IL-6) and tumor-necrosis factor α (TNFα), leading to a low chronic inflammatory state." (PMID 34940598, 2021). "Obesity can also modify pharmacokinetics of anti-TNF and other biologic agents, leading to increased drug clearance, shorter half-life and lower serum trough drug concentrations." (PMID 33499118, 2021). "Consistent with our study, type 2 diabetes mellitus, obesity, and insulin resistance result in persistent production of proinflammatory cytokines such as TNF-α, IL-1β, and IL-6, which typically inhibit adipogenesis." (PMID 34051860, 2021). "In our study, the ELISA data illustrated the effects of MLB supplementation on IL-6 and TNF-α levels in the serum of mice with HFD-induced obesity." (PMID 35010979, 2021).
Obesity (continued). "On the contrary, the mean concentration values for the inflammatory markers IL‐6, IL‐8, and TNF‐α were slightly higher in underweight/normal weight participants than in those with overweight/obesity." (PMID 33680494, 2021). "While diet-induced obesity induces a population of CD11c+ ATMs characterized by M1 phenotypes (high expression of iNOS and TNF-α) that drive immunometabolic disorders in WAT." (PMID 34108967, 2021). "In particular, three studies found an association between vegetable and fruit intake and lower levels of CRP, and IL-6 and TNF-α, both in healthy males and females, as well as in males and females with obesity." (PMID 33503979, 2021). "Circulating lipopolysaccharide levels are usually increased in patients with type 2 diabetes and/or obesity, and lipopolysaccharide has been reported to suppress megalin expression through the induction of TNFα expression in cultured PTECs35." (PMID 33441916, 2021). "In an animal model, obesity was shown to be related to an inflammatory status by secreting proinflammatory cytokines such as TNF-α and interleukin-6." (PMID 33407178, 2021). "Both obesity and hyperglycemia promote the release of inflammatory mediators, like TNF-α, or IL-6, released mediators stimulate macrophages and other innate immune cells, as well as some apoptosis-related signaling pathways, such as Fas/FasL signaling pathway." (PMID 32982969, 2020). "Increased production of TNF-α in human adipocytes is positively correlated with the degree of obesity, insulin level, and insulin resistance." (PMID 32375231, 2020). "In particular, serum and adipose TNF-α are often elevated in individuals with obesity and/or type 2 diabetes and correlate with the severity of insulin resistance and with levels of ceramides." (PMID 33072120, 2020). "Among individuals with obesity, visceral fat activates adipose tissue to make large amounts of adipokines and cytokines, such as tumor necrosis factor α, interleukin (IL)-6, and IL-8." (PMID 33374470, 2020). "During obesity development, pro-inflammatory cytokines, such as TNF-α,derived from adipocytes and macrophages, organize a paracrine loop that leads to inflammation in the adipose tissue and then increase the secretion of more pro-inflammatory molecules." (PMID 32143330, 2020). "Obesity induces insulin, IGFs, leptin, IL-6, TNF-α, CCL2, and PAI-1, reduces adiponectin, and disturbs gut microbiota and bile acid homeostasis." (PMID 32486076, 2020). "With respect to lifestyle factors predicting response, a recent systematic review and meta-analysis has quantified the effect of obesity on response to anti TNFα therapy across a range of immune-mediated inflammatory diseases." (PMID 31990352, 2020). "Patients affected by obesity showed a severe consequence of COVID-19, due to the high concentrations of TNF-α, MCP-1 and IL-6 produced in the meantime by visceral and subcutaneous adipose tissue and by innate immunity." (PMID 33160363, 2020). "In settings of obesity, TNF-α has been considered mainly pro-inflammatory as it activates immune cells particularly monocytes and macrophages into inflammatory state, M1 versus M26." (PMID 33033337, 2020). "Among cytokines, the most related to obesity and insulin resistance are tumor necrosis factor-α (TNF-α) and interleukin-6 (IL-6)." (PMID 33167421, 2020). "The obesity-induced inflammatory microenvironment is a major drive of tumor progression, characterized by the presence of proinflammatory cytokines such as TNF-α." (PMID 32477009, 2020). "Of 38 plasma proteins analyzed, six (CCL3, IL-1β, IL-1RA, IL-10, IL-17, and TNFα) were upregulated specifically in ccRCC subjects with obesity versus tumor-free controls with obesity." (PMID 32469992, 2020). "Considering that the M1 macrophages produce various types of inflammatory cytokines, such as TNF-α and IL-1β, which play an important role in the propagation of obesity-related inflammation, we thus focused on the pro-inflammatory cytokines in M1-sup." (PMID 32699606, 2020).
Obesity (continued). "TNF-α is also known to contribute to metabolic inflammation and insulin resistance, while in obesity, increased levels of TNF-α have been detected in adipose tissue and skeletal muscle together with infiltration of activated monocytes/macrophages." (PMID 32751118, 2020). "A decade later, macrophages were identified as the main source of TNF-α and other pro-inflammatory molecules (IL-6 and iNOS) in obesity." (PMID 32140136, 2020). "Chronic inflammation mediated by HFHSD-induced obesity is marked by increased pro-inflammatory cytokines such as TNF-α, IL-1β, and IL-6 in circulation." (PMID 32143330, 2020). "There is ample evidence that TNF-α is involved in the induction of obesity-related insulin resistance." (PMID 33322719, 2020). "Adipose tissue has been shown to regulate inflammatory immune responses in cartilage People and animals affected by obesity exhibit higher serum levels of TNF-α, IL-1 and IL-6, all from macrophages in adipose tissue." (PMID 33409277, 2020). "The G-308A polymorphism was also found to be associated with insulin sensitivity and increased production of leptin, suggesting an impact of TNF-α gene on obesity and obesity-related health complications." (PMID 30900134, 2020). "For example, during the development of obesity, pro-inflammatory cytokines such as TNF promote insulin resistance in adipose tissue." (PMID 33150865, 2020). "Diverse cell types like adipocytes, ASCs, and immune cells in obesity secrete and release various proinflammatory factors including IL-6, IL-1, TNF-α, leptin, and MCP-1." (PMID 32806722, 2020). "According to TNFα elevations in obesity shown by other working groups, we were able to show an elevation of hepatic TNFα expression in the HFD group too, but also in the CD group compared to the SD group." (PMID 33317065, 2020). "In this study, we aim to look into the correlation between TNF-alpha, insulin resistance, and HBA1c level in addition to the association between TNF-alpha, obesity, and diabetes." (PMID 32089876, 2020). "In fact, lipocalin expression in adipocytes is regulated by obesity and TNF-α and it can, in turn, induce insulin resistance." (PMID 31991770, 2020). "Evidence also supports the role of obesity-induced inflammation (IL-6, TNF-α, and leptin) in Tamoxifen® and anti-VEGF acquired breast cancer drug resistance." (PMID 32257945, 2020). "SLKDT intervention significantly inhibited obesity‐induced inflammation by decreasing the proinflammatory factors IL‐6, TNF‐α, IFN‐γ, and IL‐1β and increasing the anti‐inflammatory cytokines IL‐4 and IL‐10." (PMID 32884731, 2020). "In obesity, the secretion of multiple cytokines including IL-3, IL-7, IL-8, TNFα and chemokines including monocyte chemotactic protein-1 (MCP-1, also called Chemokine C-C motif ligand 2 (CCL2)), are upregulated." (PMID 33105727, 2020). "TNF-α is a pro-inflammatory cytokine and is considered to be a major factor in the development of obesity-induced inflammation." (PMID 33298044, 2020). "Obesity promotes a drastic change in the secretion profile of the adipose tissue, marked by the release of proinflammatory cytokines, including TNFα and IL-6, which can directly regulate inflammation, and, by extent, insulin resistance." (PMID 33257747, 2020). "Obesity and hyperhomocysteinemia induce chronic inflammation and oxidative stress and there is a significant positive correlation between Hcy and TNF-α concentration in groups of hypertensive patients (r = 0.48; p < 0.0001)." (PMID 32252416, 2020). "Previous reports demonstrated that increased macrophage infiltration in the adipose tissue and in the kidney, as well as augmented TNF-alpha expression in animal models of obesity, play a pivotal role in inducing kidney disease." (PMID 31919470, 2020). "The target of TNFα using either chemical inhibition or genetic KO models has shown to improve endothelial function in the obesity, diabetes, or myocardial ischemia/reperfusion model." (PMID 32190663, 2020).
Obesity (continued). "Resistance exercise was able to decrease oxidative stress and TNF‐α content in the heart of mice with diet‐induced obesity." (PMID 32761844, 2020). "By inhibiting insulin-stimulated tyrosine phosphorylation of insulin receptor and insulin receptor substrate-1, TNF-α can play a crucial role in systemic insulin resistance and also decipher a clear link between obesity, insulin resistance and T2D." (PMID 32188105, 2020). "Leptin concentration in plasma is increased in obesity, and high levels of leptin lead to the production of pro-inflammatory cytokines, including TNF-α and IL-6." (PMID 32796637, 2020). "Metabolic syndrome and obesity evolve with chronic inflammation due to higher NF-κB activity and pro-inflammatory cytokine production, such as IL-1, interleukin-6 (IL-6) and tumor necrosis factor-α (TNF- α)." (PMID 32962761, 2020). "Leptin promotes inflammatory responses in obesity, while adiponectin inhibits TNF-α production in macrophages and is considered to have anti-inflammatory properties." (PMID 33086562, 2020). "Obesity often leads to type 2 diabetes mellitus, via the increased production of proinflammatory cytokines such as tumor necrosis factor-α (TNFα)." (PMID 33257747, 2020). "These unexpected and beneficial results are called the “obesity paradox”, as adipose tissue is a potent source of pro-inflammatory cytokines such as tumor necrosis factor α (TNFα) and interleukin-6 (IL-6)." (PMID 32126127, 2020). "The non-reference allele frequency in this study was 0.084, which is similar to the non-reference allele frequency of 0.11 found in Polish Labrador retrievers (n = 136) in a study on the relation between polymorphisms in RETN, TNF and IL6 and obesity in dogs." (PMID 33142854, 2020). "Adipose tissue in 25-week-old α7−/− mice had significantly higher expression of genes encoding for TNFα, IL-6, F4/80 and IL-15 as well as CXCL1, which are associated with obesity." (PMID 32708537, 2020). "Further, corroborating the literature, we observed that obesity increased serum levels of proinflammatory cytokines TNF-α and IL-1β, and this improvement on inflammatory profile culminated in a lower hepatic sensitivity to insulin." (PMID 32847099, 2020). "Let-7a-5p functional analysis has 32 significantly enriched pathways and the novel pathways included TNF signaling pathway and Notch signaling pathway which implied its involvement in obesity." (PMID 32366215, 2020). "Specifically, we will investigate the effect of obesity and diabetes separately on the level of TNF-alpha, and we aim to recruit participants with BMI higher than 30 kg/m2." (PMID 32089876, 2020). "For instance, IL-6 and TNFα released by COVID-19 are also triggered by malaria and obesity as far as inflammation-induced insulin resistance is concerned." (PMID 33134395, 2020). "The down-regulation of Col6a3 mRNA upon TNF-α treatment in 3T3-L1 cells is consistent with COL6A3 down-regulation in the context of inflamed adipose tissue from people with obesity, and up-regulation after bariatric surgery and diet-induced weight loss." (PMID 33214660, 2020). "From literature reviews on obesity-related genes, the role of pro-inflammatory cytokines (TNF-α, IL-6, IL-1) is known, while that of anti-inflammatory molecules is less studied." (PMID 32228494, 2020). "A significant decrease of IL-6 and TNF-α levels were observed in the liver of HFD-induced obesity model after exposure to several natural products and their fermented products." (PMID 32948162, 2020). "Increased levels of pro-inflammatory cytokines, such as TNF-α, IL-1β, IL-6, and IL-12, were observed in the intestinal tissue of mouse models with obesity, which was consistent with the present findings." (PMID 33329010, 2020). "A persistent increase of circulating levels of TNF-α occurring during obesity or aging has an important role in pathogenesis of systemic insulin resistance." (PMID 31963662, 2020).
Obesity (continued). "TNF-α is central to the pathogenesis of disorders involving inflammation, such as obesity, which is characterized by chronic inflammation possibly via upregulation of TNF-α that activates the inflammatory cascade and affects various organ functions." (PMID 32708317, 2020). "GIP also increases IL-6 expression and production in adipocytes in the presence of TNF-α, which is induced by obesity and enhances HFD-induced insulin resistance through IL-6 signaling." (PMID 31977316, 2020). "A high-profile report of obesity-induced inflammation was a study in the early 1990s showing elevated TNFα expression in the AT of genetically obese mice." (PMID 33292104, 2020). "Next, we wanted to know if IRF5 expression changes in the adipose tissue were consistent with the tissue expression of TNF-α which is a signature inflammatory adipo-cytokine involved in the pathophysiology of obesity/T2D." (PMID 32188105, 2020). "This phenotype was further exaggerated in the context of obesity, where cholangitis induced in NLRP3-deficient obese mice resulted in further exacerbated histopathology and increased levels of IL-13 and TNFα, suggesting a diet-specific profile." (PMID 32716024, 2020). "Decrease in macrophages expressing TNF-α in obese mice is especially relevant since TNF-α is a very important cytokine in the pathophysiology of obesity and insulin resistance." (PMID 33266248, 2020). "Secretion of inflammatory cytokines (eg TNFα, IL‐6) and increased lipolysis can also occur during obesity‐related complications." (PMID 32458441, 2020). "As previously discussed, the chronic inflammation presented in the lung during obesity leads to a cytokine storm by overexpressing pro-inflammatory mediators, such as IL-6 and TNF-α." (PMID 32849309, 2020). "In obesity, circulating levels of proinflammatory cytokines, including TNF-α and IL-6, are elevated and the main sources of these inflammatory mediators are hepatic and white adipose macrophages." (PMID 32971975, 2020). "Adipocytes in obesity simultaneously secrete lower levels of adiponectin and elevated levels of cytokines and chemokines, such as TNFα, IL-6, MCP-1, and SAA." (PMID 32158768, 2020). "The clinical response to TNFα inhibitors is attenuated by obesity, an effect that is less pronounced with IL-6 inhibitors and the B-cell depletion agent rituximab." (PMID 32183053, 2020). "Given the inhibitory effects of TNF-a on adiponectin expression, we have shown that silibinin-induced suppression of TNF-a restored adiponectin expression which augments beneficial anti-obesity effects of silibinin." (PMID 31973745, 2020). "It has been shown that in a group of subjects with a BMI of 27 to 35 kg/m2 there is a statistically significant relationship between TNFα locus and obesity and hypertension loci." (PMID 32443588, 2020). "Mast cells are also known to play a role in adipose tissue remodeling in obesity, promoting the inflammatory phenotype of adipose tissue by secreting inflammatory molecules such as TNF and pro-angiogenesis molecules such as chymase." (PMID 33584724, 2020). "This is in line with previous work which shows that when adipocytes enlarge (hypertrophy) in obesity, they release TNFα and insulin-like growth factor which stimulate hyperplasia." (PMID 32290353, 2020). "IL-6, TNF, IL-1β and MCP-1 levels are elevated in kidneys from a diet-induced obesity rat model, associated with increased kidney fibrosis and sclerotic lesions." (PMID 32508807, 2020). "While the EpiCAT expression of resistin, leptin and TNF-α increase in obesity, the expression of adiponectin is markedly reduced." (PMID 33282920, 2020). "In animal models of HFD-induced obesity treatment with metformin led to the downregulation of TNFα levels and an increase in Tregs number, parallel to the improvement of adipose tissue, muscle, and liver histology." (PMID 32397353, 2020).